SYT13 (synaptotagmin 13)
Diseases named in the same sentence as SYT13 in open-access papers (continued):
Sharing a sentence is not in itself a finding about the gene and the disease.
cancer (8 papers, 2017 to 2022). A tumor composed of atypical neoplastic, often pleomorphic cells that invade other tissues. "Although PCR array analysis revealed the association between SYT13 and other cancer-related genes that are mainly expressed in ER-positive BC, these observational results are not capable of determining the crosstalk between these genes." (PMID 34677264, 2021). "Our study reveals a critical function of Syt13 in epithelial cell invasion and highlights the importance of our mechanistic findings in the context of cancer cell dissemination." (PMID 35927244, 2022). "Remarkably, SYT13 is also upregulated in several cancer cell types, and its inhibition reduces cancer cell metastasis." (PMID 35927244, 2022). "Further, SYT13 is upregulated in several cancer cell types, such as gastric and colorectal cancers as well as lung adenocarcinoma." (PMID 34830411, 2021). "Regarding the significance of SYT13 expression, it is necessary to take into account the biological differences between breast and other cancers that have been reported previously." (PMID 34677264, 2021). "The inhibition of Syt13 using antisense oligonucleotides hampers cancer cell metastasis and progression." (PMID 34830411, 2021). "Initially, we had anticipated that patients with advanced BC would have higher SYT13 mRNA expression levels, which indicates a poor prognosis, as demonstrated in other cancer types." (PMID 34677264, 2021). "Studies have reported the potential oncogenic role of SYT13 in human cancer." (PMID 36522312, 2022). "SYT13 could play an important role in regulating multiple signal cascades in human cancer." (PMID 36522312, 2022). "Thus, SYT13 is specifically expressed in primary cancer tissues from such patients, and in a mouse model of peritoneal metastasis, intraperitoneal administration of an SYT13-specific small interfering RNA (siRNA) significantly inhibits the growth of peritoneal nodules and prolongs survival." (PMID 33230476, 2020). "We finally obtained eight bona fide cancer driver genes, including CEP57, HNRNPL, KLF5, OXA1L, PAFAH1B1, RBM39, SYT13, and TFDP1." (PMID 31925297, 2020). "Furthermore, the levels of SYT13 mRNA in peritoneal nodules were decreased in the presence of increasing concentrations of the ASOs, suggesting their stabilities in intraperitoneal cavity and ascites fluids, which enhance their incorporation into cancer cells in the peritoneum." (PMID 33230476, 2020). "Other genes, such as ALOXE3, HBQ1, KREMEN2, SYT13, DOK7, CDC5L, and FBXO6, have been reported in several cancers." (PMID 28404969, 2017). "Although the roles of SYT13 in promoting tumorigenesis, anti-apoptotic effects, and metastases have been reported in several cancers, no studies have investigated the significance of SYT13 in BC." (PMID 34677264, 2021). "In addition, we noticed seven of them have been included in the latest version of The Network of Cancer Genes35 (KLF5, OXA1L, RBM39, and TFDP1) or CancerMine36 (HNRNPL, KLF5, PAFAH1B1, SYT13, TFDP1), two manually curated cancer gene databases, further confirming our findings." (PMID 31925297, 2020).
tumor (7 papers, 2013 to 2024). "Polymerase chain reaction (PCR) array analysis was conducted to determine the correlation between expression levels of SYT13 and other tumor-associated genes." (PMID 34677264, 2021). "These genes are known as key genes in the ER signaling pathway that contributes to tumor progression, especially in ER-positive BC, suggesting involvement of SYT13 in the ER signaling pathway in BC cells." (PMID 34677264, 2021). "Synaptotagmin 13 (SYT13) is identified as a putative liver tumor suppressor gene, complementing a molecular defect in GN6TF liver tumor cells and giving rise to tumor suppression through induction of rat WT144." (PMID 27786176, 2016). "Moreover, the results of q-RT PCR showed that CTSV, RGS4, SYT13 and NPTX1 were highly expressed in tumor tissues compared with adjacent tumor tissues, while SLC25A15, ENTPD2 and CA8 were low expressed." (PMID 36684237, 2022). "The cluster of upregulated genes contained those mainly involved in metabolism such as GGT1 (gamma glutamyl transferase 1), vesicular traffic/secretion such as SYT13 (synaptotagmin XIII) and tumor suppression such as ARMCX3 (armadillo repeat-containing X-linked protein 3) and ARMCX6." (PMID 30337535, 2018).
infection (1 paper, 2023). The state of being infected such as from the introduction of a foreign agent such as serum, vaccine, antigenic substance or organism. "While the levels of TREM1 are found up-regulated during the course of the disease we found a negative correlation for SYT13 and IL1F10 which implicate that their downregulation during the course of infection may negatively impact the host response to infection." (PMID 38283341, 2023).
neurological disorders (1 paper, 2022). "Thus, our findings have broader implications and may help to understand the molecular action of Syt13 in the pancreas, but also during neurogenesis and in neurological disorders." (PMID 35927244, 2022).
SYT13 also shares sentences with these, for which no sentence is quoted: colorectal cancer (2 papers); allergies (1); cervical adenocarcinoma (1); hyperthyroidism (1); Lewy body diseases (1); lung carcinoma (1); lymph node metastasis (1); metastasis (1); neurodegenerative disease (1); neurodevelopmental disorder (1); spinal muscular atrophy (1).